CPA5 (carboxypeptidase A5)
Tractability: Antibody: UniProt places it where antibodies can reach, with medium confidence; UniProt predicts a signal peptide or a membrane-spanning region; its Gene Ontology location is reachable by antibodies, with medium confidence.
Gene: Protein-coding gene on chromosome 7 (130,344,816 to 130,368,730, forward strand). Ensembl gene ENSG00000158525.
Subcellular location: Secreted
Subcellular location (Human Protein Atlas): Nucleoplasm; Predicted to be secreted
Gene Ontology:
Molecular function: metallocarboxypeptidase activity; peptidase activity; zinc ion binding
Biological process: proteolysis
Cellular component: extracellular region
Genetic constraint (gnomAD): Loss-of-function variants: 33 observed, 39.76 expected, observed/expected ratio (o/e) 0.83, 90% interval 0.63 to 1.11. The upper end of that interval is the gene's LOEUF score, 1.11, which puts it in group 4 of 6, group 1 being the genes least tolerant of losing a copy. Missense variants: 433 observed, 498.08 expected, observed/expected ratio (o/e) 0.87, 90% interval 0.8 to 0.94. Synonymous variants: 176 observed, 192.06 expected, observed/expected ratio (o/e) 0.92, 90% interval 0.81 to 1.04.
Homologues: Orthologues: chimpanzee CPA5 (99% identical), macaque CPA5 (96% identical), pig CPA5 (88% identical), dog CPA5 (88% identical), guinea pig CPA5 (85% identical), mouse Cpa5 (84% identical), rat Cpa5 (83% identical), rabbit CPA5 (82% identical), Caenorhabditis elegans T06A4.1 (34% identical), Drosophila melanogaster CG3108 (33% identical), Caenorhabditis elegans sdc-3 (32% identical), Caenorhabditis elegans Y59C2A.1 (32% identical), and 17 more. Paralogues in human: CPA1 (58% identical), CPA2 (52% identical), CPA4 (49% identical), CPB2 (36% identical), CPB1 (36% identical), CPA6 (36% identical), CPA3 (34% identical), CPO (26% identical).
Diseases named in the same sentence as CPA5 in open-access papers:
CPA5 is named in the same sentence as 5 diseases in open-access papers, as found by Europe PMC text mining. Sharing a sentence is not in itself a finding about the gene and the disease. The quoted sentences say what the papers report.
lung neoplasm (1 paper, 2013). A benign or malignant, primary or metastatic neoplasm involving the lungs. "On the other hand, long arm of chromosome 7 possesses imprinted domain in 7q32-qter which including MEST1, MESTIT1, COPG2IT1loci and a group of four carboxypeptidase A (CPA) genes (CPA1, CPA2, CPA4, CPA5), which are seem to be important (mainly MEST) in the initiation of breast and lung neoplasms." (PMID 23288724, 2013).
mast cell diseases (1 paper, 2016). "The research of CPA5 is focus on mast cell diseases in zebrafish." (PMID 27183310, 2016).
CPA5 also shares sentences with these, for which no sentence is quoted: Liver abscess (2 papers); abscess (1); malignant neoplasm (1).